RNU6-924P (RNA, U6 small nuclear 924, pseudogene)
Gene: Small nuclear RNA gene on chromosome 19 (46,306,470 to 46,306,577, reverse strand). Ensembl gene ENSG00000199796.
Homologues: Orthologues: chimpanzee U6 (100% identical), macaque U6 (91% identical), mouse Gm24097 (79% identical), guinea pig U6 (72% identical). Paralogues in human: RNU6-38P (87% identical), RNU6-1145P (85% identical), RNU6-1316P (85% identical), RNU6-29P (85% identical), RNU6-434P (85% identical), RNU6-1209P (84% identical), RNU6-28P (84% identical), RNU6-560P (84% identical), RNU6-812P (84% identical), RNU6-891P (84% identical), RNU6-1175P (83% identical), RNU6-20P (83% identical), and 1285 more.